CGAS (cyclic GMP-AMP synthase)
Diseases named in the same sentence as CGAS in open-access papers (continued):
Sharing a sentence is not in itself a finding about the gene and the disease.
cancer (continued). "Functioning as a prominent cytoplasmic DNA sensor, cGAS instigates the activation of the STING pathway in both cancer cells and DCs." (PMID 38816831, 2024). "GRB2 alleviates oncogenic replication stress, and in doing so, averts cancer immune destruction by inhibiting cGAS/STING and pro-inflammatory cytokine production." (PMID 38459011, 2024). "On the contrary, the P286R mutation in exon 9 of the DNA polymeraseε(POLE) gene activates intrinsic immunity in cancer cells and suppresses the occurrence of endometrial tumors via the cGAS-STING pathway." (PMID 39445027, 2024). "DNA that accumulates in the cytosol upon radiation stimulates interferon secretion by cancer cells following activation of the DNA sensor cGAS and its downstream effector STING." (PMID 39445027, 2024). "To broaden the therapeutic applications of IDEA, we commenced assessing its capability for cancer immunotherapy by delivering cGAS, a key intracellular immune regulator." (PMID 38518087, 2024). "In response to abnormally exposed double-stranded DNA in cytoplasm of cancer cells, activated cGAS synthesizes cGAMP, a second messenger, which binds to and activates STING signaling." (PMID 39242811, 2024). "Simultaneously, cancer cell-derived dsDNA activates the DC cGAS-STING axis to release IFN and other cytokines by activating the IRF1- and NF-κB-mediated signaling pathways, respectively." (PMID 38474078, 2024). "VPS34 inhibition in cancer cells triggers activation of the cGAS–STING pathway and thereby induces a type I interferon response leading to CCL5/CXCL10 chemokine secretion." (PMID 38506049, 2024). "To explore how cGAS localization is regulated, we analysed its subnuclear distribution in cancer cells." (PMID 39080411, 2024). "Radiation therapy leads to accumulation of dsDNA in cancer cells, which can be monitored by cGAS as a cytosolic DNA sensor, leading to activation of cGAS/STING signaling." (PMID 38817608, 2024). "Sensing of endogenous DNA in cancer cells through the cGAS-STING pathway facilitated by DNA-damaging agents has been proposed to initiate anti-tumoral responses." (PMID 40012911, 2024). "In accordance with previous observations in other human cell lines, we found that cancer cells depleted of Senataxin activate interferon I and interferon-stimulated genes transcription in a cGAS-dependent manner." (PMID 39120648, 2024). "Analysis of The Cancer Genome Atlas (TCGA) database, which classifies 18 different types of malignant tumors, has revealed variations in the expression of key genes involved in the cGAS-STING signaling mechanism between normal and cancerous tissues." (PMID 38545114, 2024). "These variations in expression highlight the potential of the cGAS-STING pathway as an attractive target for cancer therapy." (PMID 39295867, 2024). "Targeting cGAS presents a promising avenue for cancer therapy; however, there are inherent risks to these therapies." (PMID 39050748, 2024). "Acute genomic stressors induced by radiation, cisplatin, and intrinsic DNA damage are known to generate cytosolic DNA responsible for cGAS-STING activation in cancer cells." (PMID 39204392, 2024). "Taken together, the induction of the cGAS/STING response by the combined drugs highlights a potential avenue for enhancing the innate immune response within cancer cells." (PMID 39412086, 2024). "cGAS-STING-dependent IL-6 production contributes to the survival of chromosomally unstable cancers in an IL-6-STAT3 dependent manner, at the same time inhibiting STAT1 signaling, preventing apoptosis and promoting cell survival and growth." (PMID 38660307, 2024). "The incorporation of Mn2+ within bioactive glass (BG) can activate the cGAS‐STING immune pathway to elicit robust immune response for cancer immunotherapy." (PMID 38704692, 2024). "Yet, the regulation and mechanism of cGAS-STING pathway in cancer immunity remain to be fully understood." (PMID 38177099, 2024).
cancer (continued). "Some cancer cells were described to bypass the cGAS-STING-dependent immune response by either modulating cGAS expression, or by suppressing its functions, thereby participating in immune evasion." (PMID 38389103, 2024). "cGAS/STING activation is essential for efficient cancer therapy including radiation, chemotherapy and anti-PD-1/PD-L1 therapies." (PMID 39469633, 2024). "In the last years, ENPP1 has become an attractive target for immunotherapy because of its expression on cancer cells and its capacity to modulate the cGAS/STING pathway." (PMID 39694917, 2024). "We believe that modulating the cGAS-STING pathway will become an effective strategy for the development of drugs to treat cancer and other autoimmune or inflammatory diseases in the future." (PMID 38999073, 2024). "As an essential intracellular immune activation pathway, the cGAS‐STING pathway has attracted broad attention in cancer treatment." (PMID 38233164, 2024). "After 12–18 Gy irradiation, DNA exonuclease Trex1 is produced in different cancer cells, which degrades cytoplasmic DNA, leading to the reduction of dsDNA required for cGAS/STING activation and inhibiting the antitumor immune effect." (PMID 39834588, 2024). "To elucidate the role of the cancer cell-intrinsic cGAS-STING pathway in the upregulation of DC activation markers induced by T-DXd, we performed coculture experiments using NCI-N87 cells pretreated with a STING inhibitor or an IFN-I neutralizing antibody." (PMID 39449023, 2024). "The IFN-β, CXCL10, and IL-6 expression in MTHMS + L group elevated significantly both in cancer cells and BMDCs, evidencing the effective cGAS-STING pathway activation." (PMID 37221157, 2023). "Extracellular vesicles (EVs) are crucial in carcinogenesis and metastasis and should be explored in context of cancer vaccines and the cGAS/STING pathway among MICs." (PMID 37380989, 2023). "In parallel, either STAT1 knockdown in CAFs or cGAS/STING knockout in cancer cells significantly repressed tumor growth and SLC14A1+CAF formation in vivo, concomitantly enhancing the chemotherapy sensitivity." (PMID 37079123, 2023). "In cancer cells, endogenous or therapy-induced DNA damage leads to the abnormal presence of DNA in the cytoplasm, which triggers the activation of cGAS (cyclic GMP–AMP synthase) and STING (stimulator of interferon genes)." (PMID 37036972, 2023). "IFN can also change the cancer microenvironment by activating the CGAS‐STING pathway, thereby inhibiting the proliferation of cancer cells and inducing their apoptosis." (PMID 36727544, 2023). "Here, we report that the protein arginine methyltransferase, PRMT1, methylates cGAS at the conserved Arg133 residue, which prevents cGAS dimerization and suppresses the cGAS/STING signaling in cancer cells." (PMID 37193698, 2023). "The first potential point of activation of cGAS–STING pathway is within the cancer cells themselves following detection of cytosolic DNA from micronuclei for instance." (PMID 37534795, 2023). "In recent years, accumulated evidence has suggested that dysregulation of the cGAS-STING pathway is involved in cancer pathogenesis, including LUAD." (PMID 37667220, 2023). "Future studies are required to investigate, at the mechanistic level, how cancers with frequent chromosome missegregation cope with cGAS-STING signaling pathway." (PMID 36717545, 2023). "The beneficial roles of cGAS-STING signaling in cancer progression have recently gained considerable attention." (PMID 36861445, 2023). "Intriguingly, CIN+ cancers were found to circumvent immune surveillance through the amplification of oncogenes, which yielded inhibition of the cGAS-STING pathway and reduced production of type I IFN." (PMID 38067140, 2023). "It has been shown that ENPP1 is increasingly up-regulated as cancer cells become metastatic, and this enhances cancer cell migration in a cGAS-dependent manner." (PMID 37534795, 2023).
cancer (continued). "We aimed to elicit robust antitumor immunity by preventing viral inactivation of the cGAS/STING/IRF3 pathway after infection of cancer cells." (PMID 37016144, 2023). "cGAS-STING-mediated type I interferon responses inhibit the proliferation of cancer cells, regulate cell chemosensitivity, and are involved in cancer immunoediting." (PMID 38065948, 2023). "Indirect STING activation can be achieved in cancer therapy through cGAS or STING-activated molecules." (PMID 37781382, 2023). "In the context of tumors, DNA from cancer cells passes through the cytoplasm of antigen-presenting cells, activating the cGAS-STING pathway." (PMID 37781382, 2023). "Encompassing the chemotherapy hybrid was a ROS-sensitive polymeric nanoparticle, which improved the delivery, DNA-damaging activity, and subsequent cGAS-STING pathway activation in several cancer cell lines in vitro." (PMID 37627155, 2023). "Given the promising role of cGAS/STING pathway in anti-cancer immunotherapy, many natural and synthetic STING agonists have been developed and tested in preclinical models and clinical trials." (PMID 37237031, 2023). "Activation of the cGAS–STING pathway also induces the expression of anti-proliferative molecules that facilitate senescence in cancer cells." (PMID 37686127, 2023). "Cancers evade the cGAS-STING-mediated signaling once DNA is sensed via targeting gene expression or suppressing their function." (PMID 37761934, 2023). "Damaged DNA fragments and micronuclei accumulated in the cytosol of irradiated cancer cells can act as damage-associated molecular patterns (DAMPs), which can be sensed by cyclic GMP-AMP synthase (cGAS) to produce cGAMP." (PMID 37208386, 2023). "The score of differentially expressed genes associated with cGAS-STING was shown to be correlated to poor OS and was significantly higher compared to other cancer types." (PMID 37190141, 2023). "The inherent duality of the role of cGAS- STING in high-CIN cancers can be outlined as follows: cancer cells attract immune cells and die, but they simultaneously activate motility and distant metastasis." (PMID 38139802, 2023). "cGAS-STING drives the IL-6 dependent survival of chromosomally instable cancers through a chromosomal instability/cGAS-STING/Stat3 /RelB /NF-κB/Stat1/ILK-6/IL-6R/JNK /ASK /cell death pathway." (PMID 37854446, 2023). "Collectively, our study demonstrates that cGAS antitumor signaling is hindered by the proto-oncogene SRC and describes how cancer-associated proteins can regulate the innate immune system." (PMID 37166992, 2023). "In this review, we summarize the many different conventional cancer therapies reported to activate the cGAS-STING signaling axis." (PMID 37627155, 2023). "In recent years, the cGAS/STING pathway has received significant attention in the context of cancer." (PMID 37189700, 2023). "The mechanism of action was attributed to ERV-induced cGAS-STING activation, and cancer cell-intrinsic cGAS expression levels showed the potential to predict chemosensitization, which delineates a strategy for salvage chemotherapy." (PMID 37138342, 2023). "Recently, some DNA-damaging drugs, such as teniposide, cisplatin, and olaparib (PARP inhibitor), have manifested the capability to activate cGAS-STING signaling in cancer cells, inducing robust antitumor immune responses." (PMID 37221157, 2023). "DNA released from cancer cells or bacteria activates cytosolic cGAS to synthesize cyclic GMP-AMP (cGAMP), which combines with STING to form dimers." (PMID 38065948, 2023). "Ultimately, cGAS or STING expression were found reduced in many cancers cell lines, a possible mechanism to circumvent the immune system." (PMID 36926349, 2023). "And based on these results, cGAS-STING agonists are therefore being developed as a novel cancer therapeutic, and a greater understanding of cGAS-STING pathway regulation is leading to a broadened list of candidate immune regulatory targets." (PMID 36926351, 2023).
cancer (continued). "Cancer cells frequently downregulate the expression and function of cGAS and STING, thus promoting malignancy." (PMID 37036972, 2023). "Simultaneously, CIN promotes inflammatory phenotypes in cancer cells as a result of chronic cGAS-STING pathway activation, which ultimately leads to mobilization of immune cells to clear CIN+ cells." (PMID 38067140, 2023). "After adjusting for age, sex, location, and cGAS expression, elevated STING expression was significantly associated with stage IV cancer in a multiple logistic regression model (β = 1.849, SE = ±0.8643, p = 0.0324)." (PMID 37444620, 2023). "Increased IFN signaling in cancer can also be a consequence of the release of double-stranded DNA into the cytoplasm that induces the synthesis of cyclic GMP-AMP (cGAMP) by cGAMP synthase (cGAS) upstream of STING." (PMID 38304252, 2023). "First, in different types of cancer, cGAS-STING inhibits the cell growth cycle through cellular senescence, necrosis, and apoptosis." (PMID 36936940, 2023). "This has led to a significant interest in harnessing cGAS–STING signalling in cancer therapy and the development of STING agonists." (PMID 37534795, 2023). "The emergence of cGAS-STING mediated cancer immune surveillance coupled with the application of immunotherapy have inaugurated a new epoch in cancer treatment." (PMID 37920470, 2023). "Radiotherapy, chemotherapy, and other targeted therapies are frequently utilized in clinical cancer treatments due to their ability to activate the cGAS-STING pathway by inducing DNA damage, ultimately promoting an antitumor immune response." (PMID 37153627, 2023). "Apoptosis is an important weapon of the immune system to eliminate damaged or abnormal cells and increasing evidence has indicated that the cGAS-STING pathway can eliminate cancer cells through the induction of apoptosis." (PMID 36769349, 2023). "Intratumoral cGAS-STING signaling appears to be an important pathway for promoting anti-cancer immunity." (PMID 37079538, 2023). "Targeting the cGAS-STING pathway is an emerging therapeutic approach for various cancers due to compelling evidence indicating its activation in the TME elicits potent anti-cancer effects." (PMID 37448962, 2023). "Recent studies reveal that cGAS is frequently inhibited in cancer, and therapeutic targets to promote antitumor cGAS function remain elusive." (PMID 37166992, 2023). "The development of nanomedicine-based strategies for cGAS-STING pathway activation profoundly revolutionized cancer immunotherapy." (PMID 37221157, 2023). "As a result of chromosomal instability, cytosolic dsDNA in cancer cells elicits cancer immunogenicity via cGAS-STING pathway activation, which originates primarily from the vulnerable membrane of micronuclei." (PMID 36658649, 2023). "Ultimately, further investigation is needed to delineate all of the consequences of radiation-induced cGAS-STING activation in the treatment of cancer, and its potential to be exploited for immunotherapeutic purposes." (PMID 37627155, 2023). "According to The Cancer Genome Atlas dataset, cGAS and STING gene expression was detected in all types of cancer, but the expression varied according to the stage and type of cancer." (PMID 36936940, 2023). "cGAS-STING-mediated autophagy contributes to autophagy death during mitotic crises to avoid transformation of cancer cells." (PMID 37355491, 2023). "Cytosolic DNA induced from nuclear/mitochondrial DNA damage in cancer triggers the activation of cGAS-STING (cyclic GMP-AMP synthase-stimulator of interferon genes) pathway." (PMID 36747120, 2023). "In the context of cancer, the cGAS-STING pathway is activated by cytosolic DNA derived from chromosomal instability (CIN), a hallmark of cancer, or by DNA damage resulting from cancer therapy." (PMID 38203626, 2023). "Considering the importance of the cGAS–STING–type I IFN signaling pathway in cancer immunity, STING agonists are being developed." (PMID 37046775, 2023).
cancer (continued). "More recently, the cGAS/STING pathway has gained importance in modulating cancer immunotherapy responses." (PMID 37370745, 2023). "As a key pattern recognition receptor, cGAS plays a key role in the initiation and regulation of innate immunity and is expected to become a potential therapeutic target for cancer, systemic lupus erythematosus, and infectious diseases." (PMID 38114479, 2023). "Given the importance of the cGAS-STING pathway in cancer biology, novel strategies targeting this pathway have shown promising results and are currently under investigation for potential clinical utility in cancer immunotherapy." (PMID 37667220, 2023). "In this study, dual-responsive manganese-based nanoplatform (MPCZ NPs) was constructed to amplify cGAS-STING activation for cancer innate immunotherapy." (PMID 37061706, 2023). "Sufficient activation of the cGAS–STING pathway is essential for the success of DNA-damage mediated therapy in cancer." (PMID 37036972, 2023). "Cancer therapies (cGAMP treatment) via cGAS/STING pathway reprogram MICs (M2 to M1 macrophages or N2 to N1 neutrophils) to inhibit tumoral advancement." (PMID 37380989, 2023). "Although different mechanisms of SHP2-mediated STING activation in cancer cells and immune cells were suggested, the cGAS-STING signaling appears to be critically involved in anti-cancer immunotherapy." (PMID 37781354, 2023). "In this review, we summarize the many reports of cGAS-STING activation by different conventional cancer therapies, highlighting the roles of their targets in the DNA damage response." (PMID 37627155, 2023). "Contrarily, proteins that can be transferred between cells via gap junctions or exosomes, such as cyclic GMP-AMP synthase (cGAS) and miRNAs, have been found to promote brain metastasis in cancer cells." (PMID 37818447, 2023). "Overall, our work provides not only a new effective way to reprogram TME in vivo, but also a novel strategy to achieve whole-body therapeutic responses with nanozymes and the cGAS–STING signaling pathway for cancer immunotherapy." (PMID 37762239, 2023). "Their study not only explains why loss-of-function mutations in genes encoding cGAS and STING are rarely found in primary tumors, but also uncovers a highly selective and targetable vulnerability of chromosomally unstable cancers." (PMID 36717545, 2023). "mRNA encoding for IL6, a cytokine playing an essential role in the survival of cancer cells with chromosomal instability, via the cGAS/STING pathway, was also robustly increased." (PMID 37108510, 2023). "Here, by analyzing the effect of low doses of Pxl in various cancer cell lines, we show that Pxl treatment indeed results in a cGAS-dependent activation of a proinflammatory cascade." (PMID 36960066, 2023). "The potential of this approach to address some of the inherent and emerging limitations of cGAS-STING signaling in cancer immunotherapy is also discussed." (PMID 37627155, 2023). "cGAMP, formed as a result of the binding of dsDNA to cGAS in the cancer cell, can itself be transferred to the adjacent cells in TME by moving through the gap junctions or aided by tumor cell-derived exosomes." (PMID 37483598, 2023). "As summarized and discussed, activation of the cGAS/STING pathway plays important roles throughout the entire process of tumorigenesis to cancer metastasis." (PMID 37354378, 2023). "We further demonstrate that misalignment and mis-segregation during aberrant mitosis leads to pronounced micronucleation, a powerful mechanism for activation of cGAS/STING induced inflammatory signaling in irradiated cancer cells exposed to the ATM inhibitors." (PMID 36656721, 2023). "Given the importance of the cGAS–STING pathway in cancer immunity, considerable effort has been put into targeting cGAS–STING pathway pharmacologically." (PMID 37560754, 2023). "These investigations will contribute to a better understanding of the cGAS-STING pathway activation as a therapeutic target in cancer." (PMID 37781354, 2023).